MC2R (melanocortin 2 receptor)
Description:
G protein-coupled receptor for corticotropin/ACTH, primarily expressed in adrenal cortex where it plays a key role in the regulation of adrenocortical function. Upon activation, couples to G(s) protein, stimulating adenylate cyclase and activating the cAMP-dependent signaling pathway, the MAPK cascade as well as the PKA pathway, leading to steroidogenic factor 1/NR5A1-mediated transcriptional activation. Activation by ACTH facilitates the release of adrenal glucocorticoids, including cortisol and corticosterone. In addition, MC2R is required for fetal and neonatal adrenal gland development (By similarity).
Synonyms: ACTHR
Tractability: Small molecule: it belongs to a druggable protein family. Antibody: UniProt places it where antibodies can reach, with high confidence; its Gene Ontology location is reachable by antibodies, with high confidence; UniProt predicts a signal peptide or a membrane-spanning region. PROTAC: UniProt records ubiquitination sites on it. Other modalities: an approved drug acts on it.
Target class: Short peptide receptor (family A GPCR); Peptide receptor (family A GPCR); Melanocortin receptor; Membrane receptor; Family A G protein-coupled receptor
Gene: Protein-coding gene on chromosome 18 (13,882,043 to 13,915,707, reverse strand). Ensembl gene ENSG00000185231.
Subcellular location: Cell membrane
Pathways (Reactome):
Signal Transduction: G alpha (s) signalling events; Peptide ligand-binding receptors
Disease: Defective ACTH causes obesity and POMCD
Gene Ontology:
Molecular function: corticotropin receptor activity; protein binding; G protein-coupled receptor activity; melanocortin receptor activity
Biological process: adenylate cyclase-activating G protein-coupled receptor signaling pathway; positive regulation of glucocorticoid biosynthetic process; G protein-coupled receptor signaling pathway; G protein-coupled receptor signaling pathway, coupled to cyclic nucleotide second messenger; neuropeptide signaling pathway
Cellular component: plasma membrane; cytoplasm; membrane
Genetic constraint (gnomAD): Loss-of-function variants: 10 observed, 12.17 expected, observed/expected ratio (o/e) 0.82, 90% interval 0.51 to 1.39. The upper end of that interval is the gene's LOEUF score, 1.39, which puts it in group 5 of 6, group 1 being the genes least tolerant of losing a copy. Missense variants: 370 observed, 411.33 expected, observed/expected ratio (o/e) 0.9, 90% interval 0.82 to 0.98. Synonymous variants: 185 observed, 164.09 expected, observed/expected ratio (o/e) 1.13, 90% interval 1 to 1.27.
Homologues: Orthologues: chimpanzee MC2R (99% identical), dog MC2R (90% identical), rat Mc2r (90% identical), mouse Mc2r (89% identical), rabbit MC2R (85% identical), guinea pig MC2R (81% identical), pig MC2R (80% identical), zebrafish mc2r (49% identical). Paralogues in human: MC4R (47% identical), MC5R (46% identical), MC3R (45% identical), MC1R (39% identical), GPR12 (27% identical), S1PR1 (26% identical), S1PR3 (25% identical), CNR1 (24% identical), LPAR1 (24% identical), S1PR2 (24% identical), GPR6 (24% identical), S1PR5 (23% identical), and 6 more.
Diseases named in the same sentence as MC2R in open-access papers:
MC2R is named in the same sentence as 65 diseases in open-access papers, as found by Europe PMC text mining. Sharing a sentence is not in itself a finding about the gene and the disease. The quoted sentences say what the papers report.
glucocorticoid deficiency (25 papers, 2009 to 2025). "Approaching 50% of familial glucocorticoid deficiency (FGD) is caused by pathogenic variants in MC2R encoding the melanocortin receptor or in MRAP coding for the MC2R accessory protein." (PMID 39891580, 2025). "We report an Iranian patient with congenital glucocorticoid deficiency and cholestasis due to pathogenic variants in the MC2R gene." (PMID 39135905, 2024). "The cooccurrence of cholestasis and glucocorticoid deficiency illustrates the clinical heterogeneity caused by MC2R variants." (PMID 39135905, 2024). "Familial glucocorticoid deficiency (FGD) arises due to mutations in the ACTH-receptor components (MC2R, MRAP) or the general steroidogenesis protein (StAR)." (PMID 38098868, 2023). "MC2R mutations have been responsible for familial glucocorticoid deficiency, and Mc2r–/– mice mostly mimic the human phenotype, consisting of adrenal hypoplasia and insufficiency." (PMID 35166237, 2022). "Clinical exome analysis identified a new homozygous variant in MC2R gene as a putative responsible for familial glucocorticoid deficiency (FGD)." (PMID 34858908, 2021). "The importance of MC2R in adrenal physiology is exemplified by the condition familial glucocorticoid deficiency (FGD), a potentially fatal disease characterised by isolated cortisol deficiency." (PMID 31189126, 2019). "Mutations in the human MC2R gene cause familial glucocorticoid deficiency; of the 25 missense mutations identified, most result in decreased trafficking of MC2R to the cell surface." (PMID 28805746, 2017). "Two unrelated infants were affected by familial glucocorticoid deficiency due to MC2R gene mutations." (PMID 27485500, 2016). "Familial glucocorticoid deficiency (FGD) is a rare autosomal recessive disorder as a result of mutation in genes encoding either the ACTH receptor [melanocortin 2 receptor (MC2R)] or its accessory protein [melanocortin 2 receptor accessory protein (MRAP)[." (PMID 19558534, 2010). "Furthermore, a novel case is presented involving a family with cholestasis resulting from these deleterious mutations in the MC2R gene is presented, contributing to the broadening of the phenotypic spectrum associated with congenital glucocorticoid deficiency." (PMID 39135905, 2024). "Familial glucocorticoid deficiency is caused by variants in the MC2R and MRAP genes." (PMID 39135905, 2024). "In addition to MC2R, the reported incidence of another type of familial glucocorticoid deficiency in China is also lower than that in the UK and Turkey, with more patents with MRAP, AAAS or NNT mutation." (PMID 36061374, 2022). "Based on the presence of a micropenis and the later onset of hyperpigmentation, along with failed ACTH stimulation test and XY karyotype, we suspected the diagnosis of mutations of NR0B1, CYP11A1, and STAR genes or familial glucocorticoid deficiency (FGD) (MC2R, MRAP, NNT, and AAAS)." (PMID 36407315, 2022). "It should be noted that the current results obtained in macaques, together with the demonstration that osteocalcin injection can partially rescue adrenocortical hypoplasia and glucocorticoid deficiency in Mc2r–/– mice, lend support for the human translation of the bone/adrenal axis." (PMID 35166237, 2022). "In addition to glucocorticoid deficiency, Mc2r−/− mice also had significantly lower serum levels of aldosterone and catecholamines." (PMID 31189126, 2019). "The mutations in MC1R, MC2R, MC3R, and MC4R genes are associated with risk of melanoma, familial glucocorticoid deficiency, obesity, and type 2 diabetes mellitus, respectively." (PMID 41002740, 2025). "Genetic polymorphism in MC1R, MC2R, MC3R, and MC4R genes is associated with risk of melanoma, familial glucocorticoid deficiency, obesity, and type 2 diabetes mellitus, respectively." (PMID 41002740, 2025). "For the human all-tissues network, the genes MC2R and HPSE2 are central and related to diseases: glucocorticoid deficiency and urofacial syndrome respectively." (PMID 29161290, 2017).
glucocorticoid deficiency (continued). "106+1delG, in 6 individuals from 5 families with glucocorticoid deficiency, making this the second frequent mutation causing FGD unrelated to defects in the MC2R gene." (PMID 21274326, 2010). "Familial glucocorticoid deficiency (FGD) is a rare, autosomal recessive disorder characterised by mutations of the ACTH receptor (melanocortin two receptor, MC2R) or the melanocortin two receptor accessory protein (MRAP), which is required for trafficking MC2R to the cell membrane." (PMID 36060294, 2022). "Familial glucocorticoid deficiency is a rare autosomal recessive genetic disorder which belongs to a group of primary adrenal insufficiency (PAI) and is mainly caused by mutations in the MC2R and MRAP genes." (PMID 32952553, 2020). "Indeed, naturally occurring homozygous mutations of Asp 103 and 107 in MC2R, the equivalent conserved Asp residues in this receptor, lead to ACTH resistance/Familial Glucocorticoid Deficiency." (PMID 27547198, 2016). "Here, we report the results of whole-exome sequencing of 43 patients referred to us with a diagnosis of familial glucocorticoid deficiency (FGD) who were mutation negative for MC2R, MRAP, and STAR the most commonly mutated genes in FGD." (PMID 26300845, 2015). "Glucocorticoid deficiency seems unlikely to benefit from MC2R antagonism, but in certain specific circumstances, there could be a valuable role for this therapeutic option as discussed later." (PMID 27547198, 2016).
Adrenal insufficiency (11 papers, 2017 to 2026). Insufficient production of steroid hormones (primarily cortisol) by the adrenal glands. "The Mc2r-knockout (Mc2r−/−) mice was the first mouse model developed to have adrenal insufficiency with deficiencies in glucocorticoid, mineralocorticoid and catecholamines." (PMID 31189126, 2019). "This is further supported by melanocortin 2 receptor knockout (Mc2r-/-) mice which have adrenal insufficiency and reduced epinephrine levels and expression of catecholamine biosynthetic enzymes." (PMID 36255414, 2023). "Whereas initially the high ACTH led to the suspicion of primary adrenal insufficiency, the reduced potency of ACTH at the MC2R/MRAP shows that there is actually a secondary adrenal insufficiency." (PMID 35737586, 2022). "Despite this residual MC1R stimulation, these patients still have adrenal insufficiency since they lack ACTH which is the only ligand for MC2R that is present only in the adrenal cortex." (PMID 34177811, 2021). "First, in several children with familial forms of X-linked AHC (NR0B1/DAX-1), MC2R defects or TXNRD2 disruption, we were able to make a diagnosis of adrenal insufficiency early on in the presentation or whilst the child was presymptomatic." (PMID 34258490, 2021). "Please note that complete KOs of MC2R and MRAP are lethal at birth, and no standard transgenic animal model of adrenal insufficiency currently exists, to our knowledge." (PMID 34236047, 2021).
adrenal hypoplasia (7 papers, 2007 to 2022). "Taken together, these cases highlight that severe loss-of-function mutations in MC2R may be found in a significant proportion of children with primary adrenal insufficiency and who have been diagnosed as having salt losing forms of adrenal hypoplasia." (PMID 17223989, 2007). "No mutation was found in the NR0B1 and MC2R genes excluding congenital adrenal hypoplasia and FGD type 1." (PMID 21274326, 2010). "For example, FGD/FGD-like conditions (MC2R, MRAP, NNT gene defects) can present with salt loss suggestive of adrenal hypoplasia, and alterations in STAR and CYP11A1 resulting in partial loss of protein function may have a predominant FGD-like phenotype (17, –, 20)." (PMID 26523528, 2016).
Hypoglycemia (6 papers, 2016 to 2024). A decreased concentration of glucose in the blood. "Here we report a novel homozygous loss-of-function MC2R mutation in 2 siblings with hypoglycemia, recurrent infections, and low serum cortisol level." (PMID 35506146, 2022). "Hypoglycemia was a frequent finding, and hypoglycemic convulsions at presentation were more common in children with MC2R (22 of 25, 88%) and MRAP (five of nine, 56%) mutations than in children with an alternative diagnosis (5 of 43, 12%) (P < .0001)." (PMID 26523528, 2016). "While depletion of Mc2r reduced rapid locomotor response to acute stressors as expected, the neonatal lethality as a result of hypoglycemia observed in three-quarters of the Mc2r mutant mice has been reported." (PMID 35937837, 2022). "We also observed depleted glycogen stores in prebirth embryos, which would lead to compromised nutritional adaptation, severe hypoglycemia, and neonatal death, as described for Mc2r−/− mice." (PMID 29879378, 2018). "In addition to high levels of ACTH, 79% of MC2R-related patients have hyperpigmentation; hypoglycemia is also observed in 77% of patients, and seizure, jaundice, and vomiting are documented in 20%, 30%, and 14% of the affected individuals, respectively." (PMID 39135905, 2024).
Obesity (6 papers, 2021 to 2025). Accumulation of substantial excess body fat. "The KKRRP motif is important for the binding of ACTH to MC2R, explaining their hypocortisolism, but also involves loss of the PC2 cleavage site, likely causing obesity and hyperphagia through the absence of α-MSH and d-α-MSH." (PMID 35737586, 2022).
adrenocortical cancer (5 papers, 2013 to 2025). "Experiments in dogs have demonstrated that the abundance of the mRNA encoding MC2R is significantly downregulated in cortisol-secreting adrenocortical carcinomas." (PMID 23724142, 2013). "Herein, we show for the first time that JDP2 acts as a transcriptional activator of the Mc2r gene, including adrenocortical cancer cells." (PMID 28146118, 2017). "Moreover, overexpression of JDP2 in Y1 mouse adrenocortical cancer cells increases the level of melanocortin 2 receptor (MC2R) protein." (PMID 28146118, 2017). "However, more studies are needed to expand our understanding of how JDP2 coordinates with NR5A1 and FOXL2 to influence MC2R activity in adrenal glands and adrenocortical cancers." (PMID 28146118, 2017). "We showed the upregulation of the mRNA level of POMC, a precursor of ACTH, and MC2R in the GIP-treated and GIPR-expressing H295R adrenocortical cancer cell line." (PMID 25334044, 2014). "Indeed, we observed that overexpression of JDP2 enhances the level of MC2R, a critical and essential receptor for ACTH function, in mouse Y1 adrenocortical cancer cells." (PMID 28146118, 2017).
adrenal hyperplasia (4 papers, 2014 to 2024). "Functional studies showed that the inactivation of ARMC5 leads to the inhibition of apoptosis and decreases the expression of MC2R and steroidogenic enzymes which may be involved in adrenal hyperplasia." (PMID 36553033, 2022).
adrenocortical tumors (4 papers, 2012 to 2025). "In the next study, ACTH was administered at both physiological and supra-physiological doses to mice bearing MC2-R-positive adrenocortical tumours." (PMID 41369333, 2025). "Ideally, effects should be observed in cell lines more representative of the adrenal cortex; therefore, the murine Y-1 cell line derived from an adrenocortical tumour, and with endogenous levels of MC2R and MRAP expression, was obtained." (PMID 36515667, 2022).
primary adrenal insufficiency (4 papers, 2007 to 2026). A hormonal disorder that occurs when the adrenal glands fail to release adequate amounts of glucocorticoids (cortisol), mineralocorticoids (aldosterone, 11-deoxycorticosterone), and androgens (dehydroepiandrosterone) to meet physiologic needs, despite release of ACTH from the pituitary. "Familial glucocorticoid deficiency type I (FGD1) is a rare form of primary adrenal insufficiency resulting from recessive mutations in the ACTH receptor (MC2R, MC2R)." (PMID 17223989, 2007).
adenoma (3 papers, 2016 to 2021). A neoplasm arising from the epithelium. "More specifically, a few studies have demonstrated increased eutopic expression of MC2R assessed by RT-PCR or transcriptome studies in resected aldosteronomas as compared to cortisol-secreting adenomas, non-functional adenomas, and adrenocortical carcinomas." (PMID 27445975, 2016). "The expression of MC2R mRNA was shown to be upregulated in human adrenocortical neoplasms specifically in functional adenomas in contrast to non-functioning adenomas and carcinomas." (PMID 27445975, 2016). "Using a microarray approach in 10 aldosteronomas compared with five normal adrenals and 13 cortisol-secreting adenomas, the six GCPRs with highest increase in expression included LHCGR, 5-HT4R, GnRHR, glutamate receptor metabotropic 3, endothelin receptor ETB receptors, and MC2R." (PMID 27445975, 2016).
Hyponatremia (3 papers, 2007 to 2016). An abnormally decreased sodium concentration in the blood. "Fewer children with NNT (two of seven, 28%), MRAP (two of nine, 22%), and MC2R (2 of 25, 8%) mutations required mineralocorticoid replacement, although four additional children with MC2R defects had transient hyponatremia (sodium 117–133 mmol/L) that resolved without fludrocortisone treatment." (PMID 26523528, 2016). "Interestingly, both patients with severe FGD due to MC2R mutations showed mild hyponatremia at onset, without dehydration and overt salt-wasting." (PMID 27485500, 2016).
major depressive disorder (3 papers, 2022 to 2025). An episode of depression lasting two or more weeks without an intervening episode of mania. "We analyzed the transcript levels of genes associated with depression, including crhb, mao, mc2r, pomc, and prl, as well as genes related to learning and memory, including chata, creb1a, ngfb, chrna7a, and nqo1." (PMID 40265358, 2025). "The recent literature shows that three genes (MC1R, MC2R, and MC5R) increase the risk of major depressive disorder (MDD), and one gene (MC4R) is associated with an increased risk of type 2 diabetes, but its association needs to be researched further." (PMID 41002740, 2025). "Collaborative involvement of the MC1R, MC2R, and MC5R genes are implicated in the risk of major depressive disorder." (PMID 41002740, 2025). "Meanwhile, MC1R, MC2R, and MC5R genes are involved in the risk of major depressive disorder." (PMID 41002740, 2025). "Three melanocortin receptor genes (MC1R, MC2R, and MC5R) contribute to the risk of major depressive disorder (MDD), and one melanocortin receptor gene (MC4R) contributes to the risk of type 2 diabetes (T2D)." (PMID 35955479, 2022).
adrenal adenoma (2 papers, 2020 to 2021). "Previous studies have shown that APAs have higher MC2R transcript levels than normal adrenal tissue, non-functional adrenal adenomas, or carcinomas, although the levels reported have been somewhat variable." (PMID 33796077, 2021).
adrenal gland insufficiency (2 papers, 2022 to 2023). "We found that the variant in our patients resulted in an approximately 100-fold lower potency of ACTH to stimulate MC2R/MRAP, explaining their hypocortisolism." (PMID 35737586, 2022).
diabetes (2 papers, 2022 to 2025). "We previously demonstrated that alloxan-induced diabetes increased circulating corticosterone levels in parallel to augmentation in the MC2R expression in the adrenal glands." (PMID 36465619, 2022). "Immunohistochemistry evaluation of the adrenals of non-diabetic and diabetic mice revealed increased expression of ACTH receptor MC2R (respectively) and steroidogenic enzyme 11βHSD1 (respectively) in the condition of diabetes." (PMID 36465619, 2022).
hypercortisolism (2 papers, 2015 to 2017). "MC2R antagonists, which are currently under clinical development for the treatment of hypercortisolism associated to Cushing’s disease, will have thus to be evaluated in patients with primary adrenal Cushing’s syndrome due to BMAH." (PMID 25941513, 2015). "Progressive expression of POMC and ACTH by these cells then results in adrenocortical hyperplasia and hypercortisolism via activation of the cAMP/pKA pathway by the MC2R." (PMID 25941513, 2015). "Moreover, MC2R antagonists could represent a valuable alternative to anticortisolic drugs in clinical management of ACTH-dependent hypercortisolism, essentially Cushing’s disease, when removal of the source of ACTH excess is impossible or incomplete." (PMID 28228747, 2017).
hypothyroidism (2 papers, 2021 to 2022). Abnormally low levels of thyroid hormone. "Our first patient has hypothyroidism and as far as we know there are only few cases of MC2R mutations and hypothyroidism." (PMID 35506146, 2022). "The link between MC2R and hypothyroidism is not known yet; future investigation is needed to elucidate the underlying mechanism responsible for hypothyroidism." (PMID 35506146, 2022).